PPARA (peroxisome proliferator activated receptor alpha)
Diseases named in the same sentence as PPARA in open-access papers (continued):
Sharing a sentence is not in itself a finding about the gene and the disease.
steatosis (continued). "Even at low doses, both PFOA and GenX can disrupt hepatic lipid metabolism via the PPARα signaling pathway, promoting steatosis and altering the liver transcriptome." (PMID 40863893, 2025). "Loss of BAP31 impaired hepatic metabolic homeostasis by suppressing PPARα signaling, reducing fatty acid oxidation, and disrupting glycogen synthesis, leading to excessive lipid accumulation and exacerbated steatosis." (PMID 41465598, 2025). "MiR-10b regulates cellular steatosis levels by targeting peroxisome proliferator-activated receptor-alpha (PPARα) expression, as PPARα has also been found to participate in steatosis." (PMID 40941416, 2025). "Wy-14643 is a powerful PPARα agonist that can inhibit steatosis, restore insulin sensitivity, as well as lipid and adiponectin levels, thereby reducing MASLD caused by PPARα dysregulation." (PMID 41377566, 2025). "The findings of this study suggest that liver ChREBPα is linked to increased steatosis, as it positively correlates with ALT and liver PPARα expression." (PMID 41373582, 2025). "Dysregulation in any node disrupts metabolic homeostasis, as evidenced by PPARα downregulation exacerbating steatosis while FXR agonism ameliorates it." (PMID 40564141, 2025). "In contrast, we did not observe a clear FFA-treatment-dependent increase in the expression of MAP LC3β or PPARα in all donors, indicating that regenerative pathways play a lesser role in our in vitro steatosis model." (PMID 40136698, 2025). "This early time point coincided with an increase in serum concentrations of AST and cholesterol in plasma, along with microvesicular steatosis and increased expression of the cholesterol metabolism gene PPARA in the liver tissue." (PMID 38400071, 2024). "Our results showed that livers from leptin-deficient mice expressed significantly higher levels of both PPARγ (15-fold) and PPARα mRNA (>1.5-fold), suggesting that ob/ob mice exhibited increased hepatic adipogenesis and steatosis." (PMID 39201365, 2024). "Here, microvesicular steatosis was present concurrent with the heightened expression of PPARA, a gene involved in cholesterol metabolism and beta-oxidation, underscoring the metabolic dysfunction in the liver during acute SIV infection." (PMID 38400071, 2024). "The study aimed to determine the effects of a coconut oil-based HFD in an early liver carcinogenesis rat model and clarify steatosis and pexophagy when combined with PPARα CF administration in this model." (PMID 39765694, 2024). "Some studies have shown that activation of PPARα has a crucial role in preventing steatosis and in reducing inflammation and fibrosis." (PMID 39061917, 2024). "AEG-1 promotes steatosis by inhibiting peroxisome proliferator-activated receptor alpha (PPARα), a master regulator of fatty acid β-oxidation, and translationally upregulating fatty acid synthesizing enzymes, notably fatty acid synthase." (PMID 38677511, 2024). "In chronic alcohol-fed mouse models, CBD restored liver peroxisome proliferator-activated receptor α(PPARα) protein expression and improved alcohol-induced liver metabolic imbalance and steatosis." (PMID 38397045, 2024). "The fasting response involved PPARα and glucocorticoid signaling, lowering hepatic triglycerides and steatosis." (PMID 39684520, 2024). "In the present study, we clarified the involvement of pexophagy in a steatosis model with rats fed coconut oil-based HFD by administering a PPARα agonist, CF." (PMID 39765694, 2024). "In accordance with recently published results, we found that both PPARα and γ are downregulated during the pathological condition of steatosis." (PMID 37047034, 2023). "The influence of PPARα on inflammation and hepatic steatosis was demonstrated in a PPAR-/- mouse model." (PMID 37686810, 2023). "This is consistent with literature showing Hnf4α activity is decreased by fatty acids and decreased Pparα results in enhanced steatosis." (PMID 36675277, 2023).
steatosis (continued). "Meanwhile, the authors studied the beneficial effect of UA in the human hepatic cell line (HL-7702) model, where it stimulates PPARα mRNA, showing an anti-steatosis effect that was interrupted by PPARα knocking down." (PMID 37893218, 2023). "While liver-specific knockout of PPARα leads to increased plasma cholesterol levels, inflammation, and steatosis, the effects of PPARα knockout in the gut are entirely different." (PMID 38004166, 2023). "In preclinical models of NAFLD, the dual PPARα/β agonist GFT505 improves steatosis, inflammation and fibrosis." (PMID 37987033, 2023). "FXR was shown to suppress steatosis by inhibiting SREBP1c and induction on PPARα and its target, CPT1." (PMID 36839192, 2023). "In the present study, the protein expression levels of PPARα and CPT1A were decreased by HFD-induced steatosis, suggesting that reduced β-oxidation is one of the vital causes of steatosis." (PMID 37033263, 2023). "Our data also supports the observation that miR-483 inhibits PPARa expression and downregulates cell steatosis." (PMID 36980601, 2023). "PPARα agonists such as thiazolidinediones (TZDs) increase glucose utilization, lower lipid levels, decrease fibrosis/steatosis, and contribute to better cardiac functioning." (PMID 37189744, 2023). "Previous reports have suggested that PPARα activation is beneficial for improving steatosis, inflammation, and fibrosis in preclinical models of NASH." (PMID 38034083, 2023). "The KLF6 gene was highly expressed in various tissues and played a critical role in adipocyte differentiation by activating PPARα that regulated hepatic steatosis, lipoprotein synthesis, hepatic gluconeogenesis and fatty acid transport proteins in mouse." (PMID 38017423, 2023). "PPARα deletion has been found to impair fatty acid catabolism, resulting in hepatic lipid accumulation and liver inflammation in preclinical models of steatosis." (PMID 37047048, 2023). "miR-30a-3p and miR-3666, for example, protect hepatocytes from steatosis by targeting PPARα and PPARγ, respectively." (PMID 37190114, 2023). "After treatment with calcitriol, HepG2 cells in the model group showed improved intracellular steatosis, which was accompanied with higher protein expression levels of PPARα and CPT1A." (PMID 37033263, 2023). "In contrast to PPARα, the expression of PPARγ in the liver increased as steatosis develop in rodents." (PMID 35528835, 2022). "PPARα agonists have a significant curative effect in reducing steatosis, inflammation, apoptosis, and the progression of tissue fibrosis in liver of mice on a high-lipid-induced diet." (PMID 35335339, 2022). "For further investigation of the PPARα pathway in steatosis alleviation by the CS, we evaluated CPT1 expression as a target gene of PPARα." (PMID 36192786, 2022). "All these findings provide evidence on the role of PPARα-mediated peroxisome functionality in the onset of steatosis and NASH." (PMID 35625520, 2022). "Among these potential targets, PPARα, a key nuclear receptor that promotes β-oxidation, was markedly decreased in both WD-induced steatosis mice and WD/CCl4-induced NASH mice, while bicyclol with or without berberine increased its expression." (PMID 35250593, 2022). "Hepatocyte-specific PPARα knockout mice exhibit marked steatosis, inflammation, and suppressed levels of CPT1 as compared with wild-type mice in response to dietary-induced obesity." (PMID 36148775, 2022). "It is a major regulator of steatosis through peroxisome proliferator-activated receptor alpha and sterol-regulatory element binding protein-1 pathways and it is considered as a major risk factor for the progression of HCC18–20." (PMID 36123370, 2022). "A potent inducer of PPARα stimulated beta-oxidation in a model of steatohepatitis, and induced a complete clearance of steatosis together with a significant reduction of oxidative stress and oxidative injuries and prevention of inflammation and fibrosis." (PMID 35203610, 2022).
steatosis (continued). "More specifically, PPARα was hypermethylated in an in vitro and in vivo steatosis model leading to lower PPARα gene expression and protein levels." (PMID 36551797, 2022). "Conversely, metformin administration attenuated the olanzapine-induced upregulation of PCSK9, FAS, and SCD1 as well as downregulation of SCAD and PPARα, effectively improving hepatic/hepatocyte steatosis." (PMID 35379885, 2022). "Feeding mice with ethanol showed a decrease in the levels of RXRα protein, which in turn did not allow binding of PPARα/RXRα to DNA, decreasing mRNA for several genes regulated by PPARα, and therefore, the development of steatosis was favored." (PMID 34361064, 2021). "In summary, the PPARα agonistic and thus steatosis-counteracting properties of genistein were only observed in control PHHs at the protein level." (PMID 33671486, 2021). "Further investigation revealed that hsa_circRNA_0046367 acts as miRNA sponge on miR-34a, a miRNA largely studied as potential biomarker for liver diseases, consequently abolishing its inhibitory effect on PPARα and leading to steatosis." (PMID 34299336, 2021). "Our results suggest that the dual activation of PPARα and PPARγ by saroglitazar can effectively improve steatosis, fibrosis, and aspects of necro-inflammation in the HF-induced NASH model better than fenofibrate and pioglitazone." (PMID 34593018, 2021). "On the other hand, restoration of hsa_circRNA_0046367 resulted in a prevention of steatosis onset due to PPARα inhibition by miR-34." (PMID 34299336, 2021). "PPARα activation, in combination with PPARβ/δ agonism, has been shown to improves steatosis, inflammation, and fibrosis in preclinical models of NAFLD." (PMID 33926085, 2021). "Studies conducted in animals have consistently reported the importance of PPARα expression in steatosis and NASH." (PMID 34867358, 2021). "The data we obtained in Pparαhep−/− mice fed a HFD indicate that the deletion of Pparα in hepatocytes is sufficient to promote steatosis and inflammation." (PMID 32300166, 2020). "Western blot results showed that CD36 and SREBP-1c were significantly increased while PPARα decreased in db/db mice compared with that of db/m mice, indicating that hepatic steatosis was observed in db/db mice." (PMID 33551821, 2020). "In HFD, steatosis in Pparαhep−/− and Pparα−/− mice was much more severe than for WT mice, which is in agreement with their respective liver weight." (PMID 32300166, 2020). "We have shown recently that a hepatocyte-specific deletion of Pparα induces spontaneous steatosis in aging mice and blunts fasting-induced ketogenesis." (PMID 32300166, 2020). "In the current study, we investigated the role of hepatocyte PPARα in a preclinical model of steatosis." (PMID 32300166, 2020). "PPARα agonists, i.e., fibrates utilized to reduce steatosis and inflammation in human steatohepatitis, showed weak effectiveness because of the different response of human respects to rodents." (PMID 31683535, 2019). "PPARα knockout mice fed a HFD seemingly have an increased susceptibility to NASH, as shown by more advanced steatosis and increased markers of oxidative stress and inflammation." (PMID 31121839, 2019). "Taken together, studies using mouse models and pharmacological treatments have demonstrated a beneficial effect of PPARα by preventing steatosis, inflammation, and fibrosis." (PMID 31121839, 2019). "We demonstrated that CnP improves steatosis in mice through the upregulation of PPARA and its downstream targets involved in fatty acid oxidation and autophagy." (PMID 30689650, 2019). "In the liver, the non-oxidized fatty acids are diverted towards re-esterification, explaining the fasting-induced steatosis in PPARα−/− mice." (PMID 30866796, 2019). "In conclusion, the data obtained in the present study suggest that CnP attenuates steatosis through the stimulation of PPARA, CPT1, and CPT2-related β-oxidation in the liver." (PMID 30689650, 2019).
steatosis (continued). "This PPARα deletion is sufficient in promoting steatosis and hence establishes PPARα as a relevant drug target in NAFLD." (PMID 31121839, 2019). "Elafibranor (GFT505) is an agonist of both PPARα and PPARδ, that was initially evaluated in animal models, showing protective effects on steatosis, inflammation and fibrosis." (PMID 31703268, 2019). "Taken together, our data suggest that Rg3 and Rd, which are abundant in CRG, confer protection against steatosis through mTORC1-mediated induction of mitophagy and PPARα signaling." (PMID 31817227, 2019). "Fasting is sufficient to trigger steatosis in PPARα-null mice, indicating that PPARα activity is required for metabolizing free fatty acids released from adipocytes." (PMID 29954129, 2018). "Increasing fatty acid oxidation by PPARα activation can lower circulating triglyceride levels, decrease liver and muscle steatosis, and reduce adiposity, which improves insulin sensitivity." (PMID 30021644, 2018). "The interaction of ethanol with the unsaturated FA oleate worsens steatosis and FA oxidation while the short chain ceramide C2 remedies the ethanol-mediated FA oxidative defects at least in part via a PPARα-mediated mechanism." (PMID 30150688, 2018). "In this paper, we show a new molecular mechanism that MG, as an agonist for PPARα, is closely associated with the activation of AMPK and AKT in the regulation of steatosis and hyperlipidemia." (PMID 29467759, 2018). "The model predicted that activation of PPARα by lipids produces a biphasic response, which initially exacerbates steatosis." (PMID 30131870, 2018). "We further showed that the PPARα agonist GW7647 treatment significantly attenuated the PA-mediated steatosis and." (PMID 29022907, 2017). "When compared to that of the steatosis group, the circRNA group showed a dramatic increase in PPARα expression at both transcription and translation levels." (PMID 29018509, 2017). "In liver tissue of NAFLD patients and HepG2 cells with FFA-induced steatosis, PPARα expression indeed correlated to the level of circRNA_0046367 and miR-34a in positive and negative manner, respectively." (PMID 29018509, 2017). "We concluded that BMSO-mediated anti-steatosis depended on PPARα, whereas the anti-adiposity effect was PPARα-independent." (PMID 27973445, 2016). "Hepatic PPARα expression decreases in NAFLD leading to steatosis, but is enhanced following diet and exercise." (PMID 27657051, 2016). "In animal models of steatosis and steatohepatitis, the use of PPARα activators improves the disease." (PMID 27657051, 2016). "Among these molecules, Peroxisome Proliferator-Activated Receptor alpha (PPARα) is a major player, as deletion of the gene in mice leads to steatosis, hypoglycaemia, hypothermia, and reduced ketone bodies in response to fasting." (PMID 27669233, 2016). "BMSO-mediated anti-steatosis effect was PPARα-dependent, although this master regulator of lipid homeostasis was not essential for the anti-adiposity effect and α-ESA conversion of BMSO-fed mice." (PMID 27973445, 2016). "A meta-analysis of treatments of patients with NAFLD (for a median duration of 6 months) with supplements of omega 3 fatty acids showed significant ultrasonographic improvement of steatosis, likely involving a reversal of the Srebp-1c/PPARα ratio." (PMID 27446914, 2016). "This newly identified miR-34a-PPARα pathway provides a novel clue to the pathogenesis of steatosis formation in NAFLD." (PMID 26330104, 2015). "In the present study, we identified a role of miR-34a in regulating the degree of steatosis by directly targeting PPARα." (PMID 26330104, 2015). "The ability to accurately predict PPARα activation or suppression would be useful to evaluate the potential for diverse factors including chemicals to contribute to liver cancer or steatosis by affecting PPARα." (PMID 25689681, 2015). "The ability to cope with fasting-induced steatosis is controlled by the induction of lipid oxidation through PPARα activation." (PMID 25141153, 2014).
steatosis (continued). "Mice deficient for FAO-associated genes, such as MCAD, LCAD and PPARα, showed metabolic changes that were very similar to DKO mice in response to fasting, such as marked steatosis, hypoglycemia and an elevated level of serum NEFA." (PMID 24244493, 2013). "In the HepG2 cells of our study, the steatosis was increased significantly by the incubation of Ang II with decreased expression of PPARα; the treatment with aliskiren attenuated steatosis with up-regulation of PPARα." (PMID 24204981, 2013). "Of these, our group and others have demonstrated that PPARα and PPARγ are important regulators of postischemic liver injury that exert their effects on steatosis and inflammation, which is inherent in steatotic liver surgery." (PMID 22675337, 2012). "The critical role of PPARα in ameliorating steatosis is mediated through the regulation of a wide variety of genes involved in peroxisomal, mitochondrial, and microsomal FA β-oxidation systems in the liver." (PMID 22675337, 2012). "Consistent with a protective role of PPARα for IR and steatosis development, PPARα-null mice fed a Western diet develop more steatosis, oxidative stress, and inflammation in the liver than wild-type mice." (PMID 23024649, 2012). "Further analyses revealed that miR-10b induces steatosis in these cells by directly targeting PPARα and preventing its expression." (PMID 23024649, 2012). "Another common feature is the ability of both viruses in modulating PPARα and PPARγ activity/expression which are related to steatosis." (PMID 23028383, 2012). "Reduction of PPARA and Lipin1-2 decreases the hepatic capacity for fatty acid oxidation leading to steatosis." (PMID 21779369, 2011). "By inducing mitochondrial, peroxisomal, andmicrosomal fatty acid oxidation, PPARα reduces hepatic fataccumulation in the liver during the development of fatty liverdisease, and thus prevents steatosis." (PMID 17389767, 2007). "Similarly, H&E staining showed extensive steatosis in control, Pparα KO, and Cideb; Pparα double KO mice, and all of these groups had substantially more steatosis than Cideb KO mice." (PMID 40618957, 2026). "Three weeks later, livers with PPARα overexpression showed reduced steatosis." (PMID 40618957, 2026). "The enhanced efficacy of GmOLb may stem from fermentation-induced increases in ω-3 PUFAs (EPA and DHA) that regulate AMP-activated protein kinase and PPARα pathways to alleviate inflammation and steatosis." (PMID 40870774, 2025). "In addition, according to some studies, bilirubin can inhibit lipid accumulation, prevent the development of steatosis, and regulate the overall energy homeostasis of the body by binding to PPARα." (PMID 41149634, 2025). "Consequently, reactivated miR-1972 induces reductions in the transcriptional and/or translational levels of LPIN1, thereby inducing the expression of steatosis-related genes via the activation of the PPARα." (PMID 40941416, 2025). "Notably, hepatic expression of PPARα exhibits an inverse correlation with the degree of steatosis, MASH severity, and fibrosis." (PMID 40052160, 2025). "Consequently, reactivated miR-1972 decreases the transcriptional and/or translational levels of LPIN1, inducing steatosis-related gene expression via PPARα." (PMID 40941416, 2025). "In NAFLD patients, miR-34a regulates steatosis by targeting PPARα expression." (PMID 41226441, 2025). "Lanifibranor, a pan-PPAR agonist, directly activates all three PPAR isoforms, resulting in the PPARα-induced inhibition of steatosis in hepatocytes, PPARδ-induced reduction of hepatic macrophage infiltration, and PPARγ-induced reduction of hepatic stellate cell (HSC) activation." (PMID 41586160, 2025). "Moreover, PPARα is a key target of hepatic steatosis and saturated fatty acid accumulation induced by MC-LR in zebrafish." (PMID 41227594, 2025). "Other studies demonstrated that inhibiting miR-21 can mitigate steatosis by activating PPARα." (PMID 41226441, 2025).